C1QL3 (complement C1q like 3)
Description:
May regulate the number of excitatory synapses that are formed on hippocampus neurons. Has no effect on inhibitory synapses (By similarity). Plays a role in glucose homeostasis. Via AMPK signaling pathway, stimulates glucose uptake in adipocytes, myotubes and hepatocytes and enhances insulin-stimulated glucose uptake. In a hepatoma cell line, reduces the expression of gluconeogenic enzymes G6PC1 and PCK1 and hence decreases de novo glucose production (By similarity).
Synonyms: CTRP13; K100; C1ql; C1QTNF13
Tractability: Antibody: UniProt places it where antibodies can reach, with medium confidence; UniProt predicts a signal peptide or a membrane-spanning region; its Gene Ontology location is reachable by antibodies, with medium confidence.
Gene: Protein-coding gene on chromosome 10 (16,513,734 to 16,521,879, reverse strand). Ensembl gene ENSG00000165985.
Subcellular location: Secreted
Subcellular location (Human Protein Atlas): Vesicles; Cytosol; Predicted to be secreted
Gene Ontology:
Molecular function: identical protein binding
Biological process: maintenance of synapse structure; trans-synaptic signaling, modulating synaptic transmission; neurotransmitter receptor localization to postsynaptic specialization membrane; postsynaptic density assembly
Cellular component: synapse; synaptic cleft; extracellular region; glutamatergic synapse; hippocampal mossy fiber to CA3 synapse
Genetic constraint (gnomAD): Loss-of-function variants: 4 observed, 11.61 expected, observed/expected ratio (o/e) 0.34, 90% interval 0.17 to 0.79. The synonymous counts are far from expectation, so gnomAD's model fits this gene poorly and the ratio says little. Missense variants: 266 observed, 322.15 expected, observed/expected ratio (o/e) 0.83, 90% interval 0.75 to 0.91. Synonymous variants: 189 observed, 142.25 expected, observed/expected ratio (o/e) 1.33, 90% interval 1.18 to 1.5.
Homologues: Orthologues: chimpanzee C1QL3 (100% identical), macaque C1QL3 (100% identical), dog C1QL3 (99% identical), mouse C1ql3 (99% identical), pig C1QL3 (99% identical), rabbit C1QL3 (99% identical), tropical clawed frog c1ql3 (95% identical), guinea pig C1QL3 (91% identical), zebrafish c1ql3a (88% identical), zebrafish c1ql3b (82% identical), rat C1ql3 (78% identical). Paralogues in human: C1QL1 (76% identical), C1QL2 (73% identical), C1QL4 (67% identical), COL10A1 (35% identical), COL8A2 (34% identical), COL8A1 (33% identical), C1QTNF7 (32% identical), C1QTNF2 (31% identical), C1QB (31% identical), C1QTNF5 (31% identical), OTOL1 (31% identical), C1QTNF9 (30% identical), and 11 more.
Diseases named in the same sentence as C1QL3 in open-access papers:
C1QL3 is named in the same sentence as 30 diseases in open-access papers, as found by Europe PMC text mining. Sharing a sentence is not in itself a finding about the gene and the disease. The quoted sentences say what the papers report.
Obesity (6 papers, 2013 to 2024). Accumulation of substantial excess body fat. "Many of the C1ql3 correlates that differentiated lean and obese animals were related to β-cell function and have been shown previously to be associated with obesity or T2D." (PMID 31300714, 2019). "Herein, we demonstrate a streamlined approach to effectively screen and determine the function of secreted proteins in islets, and identified C1ql3 as a putative contributor to reduced insulin secretion in obesity, linking C1ql3 to an increased susceptibility to type 2 diabetes." (PMID 31300714, 2019). "Furthermore, islet cell transcriptional regulation by C1ql3 may provide insights into the mechanism underlying long-term nutritional adaptation of β-cells during obesity and may provide insight into why only a fraction of obese individuals develop T2D." (PMID 31300714, 2019). "C1ql3 was identified as one of the top regulators of islet function specifically in obesity, with an IMC of 2458 and MM of 0.92." (PMID 31300714, 2019). "By comparing regulators that were identified for lean, obese, and merged islet expression data, Cck, C1ql3, Serpina7, Creld2, Svop, Smoc1, Tgfβ3, and Serpini1 were identified to affect islet function in obesity." (PMID 31300714, 2019). "Correlation and ontology-based analyses identified C1ql3 as a hub gene with high IMC to affect islet function in obesity by modulating secretion, nuclear division, mitotic cell process, and cell division." (PMID 31300714, 2019). "Co-expression network analysis along with data filtering approaches of gene expression data obtained from islets of lean and obese mice identified C1ql3 as a hub gene affecting islet function in obesity." (PMID 31300714, 2019). "Complement 1q like-3 (C1ql3) secreted protein was identified as a hub gene affecting islet function in obesity." (PMID 31300714, 2019). "An increase in the relative mRNA abundance of C1ql3 was observed in islets of several mouse models of obesity compared to their lean controls." (PMID 31300714, 2019). "C1ql3 is expressed in β-cells, its expression is elevated in islets obtained from mouse models of obesity (HFD-induction, Ob/Ob, and Db/Db), and it inhibits insulin secretion from mouse islets and INS1(832/13) β-cells." (PMID 31300714, 2019). "The high connectivity of C1ql3 based on these attributes identified C1ql3 as a major “hub gene” affecting islet function in obesity." (PMID 31300714, 2019). "Furthermore, C1ql3 is DE (>32-fold) with obesity, and inhibits insulin secretion and the expression of genes involved in β-cell function." (PMID 31300714, 2019). "C1ql3 was identified as one of the top candidates that affect islet function in obesity." (PMID 31300714, 2019).
neuroblastoma (1 paper, 2019). Neuroblastoma (NB) is the most common solid, extracranial childhood tumor. "Overall, we found that downregulation of 7 genes (Crb1, Lrrc9, Rcn1, Rtl1, Shisa3, Six6, St18) and upregulation of 2 genes (C1ql3, Slc18A1), are strongly predictive of favorable neuroblastoma outcome, consistent with delayed tumor development in Th-MYCN/Casp2−/− mice." (PMID 30670683, 2019).
tumor (4 papers, 2015 to 2024). "Paradoxically, a group of proteins, including C1QL3, EPB41, SNX10, FGF14, GLB1L2 and TRAK2, have been reported as good prognostic markers or tumor suppressors in the NmFMC group." (PMID 38951817, 2024).
cancer (1 paper, 2015). A tumor composed of atypical neoplastic, often pleomorphic cells that invade other tissues. "DNA methylation alterations in UNC13A, SP9, GP5, C1QL3, SP8, and VWC2 have not been previously reported in cancer." (PMID 26380585, 2015).
C1QL3 also shares sentences with these, for which no sentence is quoted: atherosclerosis (9 papers); coronary artery disease (6); Insulin resistance (6); type 2 diabetes mellitus (6); metabolic disorders (3); dyslipidemia (2); fatty liver (2); Anorexia (1); arteriosclerosis (1); autistic spectrum disorder (1); cardiovascular disease (1); chronic kidney disease (1); coronary artery stenosis (1); endothelial dysfunction (1); fibrosis (1); Genetic obesity (1); Hyperglycemia (1); Impaired glucose tolerance (1); inflammation (1); kidney cancer (1); kidney inflammation (1); liver fibrosis (1); non-alcoholic fatty liver (1); polycystic ovarian syndrome (1); renal fibrosis (1); viral infection (1).